CDH1 (cadherin 1)
Diseases named in the same sentence as CDH1 in open-access papers (continued):
Sharing a sentence is not in itself a finding about the gene and the disease.
gastric cancer (continued). "Of the two individuals who carried two DV in genes other than MUTYH, one was affected with colorectal cancer and carried a DV in CHEK2 and PALB2, while the second was not personally affected with cancer but did have a family history of breast and gastric cancer and carried DV in PMS2 and CDH1 genes." (PMID 29308099, 2018). "The inactivation of CDH1 was observed with TSS methylation, and this may contribute to the characteristic feature of EBV-positive gastric cancer that they often appear as diffuse-type gastric cancer." (PMID 28903418, 2017). "The gastric cancer manifests when the complete inactivation of the CDH1 gene occurs, leading to a lack of the E-cadherin expression." (PMID 29094049, 2017). "Decreased CDH1 expression is positively correlated with gastric cancer progression; the decreased CDH1 (E-Cadherin) expression observed here might partially explain the ability of UBE2T knockdown to attenuate gastric tumor formation and growth." (PMID 28427240, 2017). "Though, the population size in our study is small and the significant results need to be confirmed in larger groups with known family history of breast and gastric cancer to better understand the interactions between AXIN2 and CDH1 genes in the development of NSCL ± P." (PMID 28376813, 2017). "Three CDH1 variants (p.R335Q, p.L630V, and p.A817V) listed as VUS in ClinVar were found in cases with CRC before age 60 and no history of gastric cancer." (PMID 29212164, 2017). "Also, treatment of gastric cancer cell lines (TMK-1, MKN-74, and MKN-7) with IL-1β has been reported to have induced the methylation of tumor-suppressor gene CDH1, based on a conventional methylation-specific PCR." (PMID 26823082, 2016). "Similarly, methylated CDH1 predicts a poor prognosis in gastric cancer patients; however, S100A6 is important in the progression and prognosis of gastric cancer, and is upregulated by epigenetic regulation." (PMID 25788990, 2015). "Cdh1 ablation in the gastric mucosa also did not result in gastric cancer, although noninvasive E-cadherin-negative cell aggregates occurred." (PMID 25757734, 2015). "In other populations in which the incidence of gastric cancer is high, there are also reports of HDGC-carrier families with large numbers of affected individuals who do not carry CDH1 gene germline mutations." (PMID 25180051, 2014). "Familial intestinal gastric cancer (FIGC) with a positive family history have also been described but so far, no germline CDH1 defects have been associated with FIGC or intestinal GCs." (PMID 24204729, 2013). "In a series of 270 CDH1 PV carriers with a follow up time of 31.1 months, 97% with a family history of gastric cancer, 58 patients were diagnosed with SRC in the absence of a macroscopic abnormality and continued 6 monthly endoscopic surveillance without progression to advanced DGC." (PMID 39261344, 2024). "We continued the qRT-PCR analysis of the samples, and among the EMT-related markers, the expression levels of mesenchymal markers CDH2 and ZEB1 genes were significantly reduced in gastric cancer cells after TGFβ gene silencing, while CDH1 expression was not significantly altered." (PMID 36119489, 2022). "Interrogation of CCLE database revealed that FZD5 is positively correlated with epithelial-related factors CDH1 (E-cadherin), OCLN (Occludin), EPCAM and ELF3, while negatively correlated with mesenchymal-related factors VIM (Vimentin), SNAI2 (Slug), ZEB1 and ZEB2 in 37 gastric cancer cell lines." (PMID 33618713, 2021). "Chan and colleagues suggest that Hp may induce CDH1 promoter methylation in non-neoplastic gastric mucosa and in gastric cancer." (PMID 34576114, 2021). "Therefore, evaluating the protein level of E-cadherin and changes in the CDH1 gene may provide promising prospects for the diagnosis, prognosis, and treatment of gastric cancer." (PMID 34422902, 2021).
gastric cancer (continued). "To determine if the synthetic lethal (SL) relationship identified between CDH1 and allosteric inhibition of AKT was present in cancer cell lines, we tested the allosteric AKT inhibitors in an isogenic cell line pair derived from NCI-N87 gastric cancer cells: NCI-N87-WT and NCI-N87-CDH−/−." (PMID 31540244, 2019). "However, screening by E-cadherin immunohistochemical staining is not feasible, because 60% of gastric cancers without E-cadherin expression and 70% of gastric cancers with aberrant expression are negative for CDH1 alterations." (PMID 30568591, 2018). "There were 938 genes more than twofold differently regulated in the c.1380delA CDH1 SB.mhdgc-1 cells (p < 0.05; FDR < 0.1) with c.1380delA CDH1 SB.mhdgc-1 cells separating on unsupervised hierarchal cluster analysis of global gene expression profiling from sporadic gastric cancer cell lines." (PMID 28460635, 2017). "Of note, two women carrying the same CDH1 VUS, currently discordant in Clinvar as either a VUS or likely pathogenic (c.1118C>T, p.Pro373Leu), had no family history of gastric cancer and therefore did not meet criteria for hereditary diffuse gastric cancer syndrome." (PMID 28649662, 2017). "Four patients in our cohort had a positive CDH1 result, two of whom did not meet International Gastric Cancer Linkage Consortium testing criteria, resulting in a frequency of 0.02% (2/8,708) positive CDH1 results in individuals who do not meet clinical criteria among those tested for the gene." (PMID 26681312, 2016). "RASSF1A, p14ARF, and MGMT; CHRNA3, DOK1, and GNMT; p16, hMLH1, MINT1, MINT2, MINT12, MINT25, and MINT31; APC, CDH1, MHL1, CDKN2A, CDKN2B, and RUNX3; CDH1; DKK3; PTEN; MGMT; TFPI2; CACNA2D3; PCDH10; SOX2; MAL; and COX2 were previously reported to be hypermethylated in gastric cancer." (PMID 26121593, 2015). "However, the current criteria for CDH1 genetic testing require histopathological confirmation of diffuse gastric cancer in at least one family member, which we did not have, and both gastric cancer cases were not diagnosed below the age of 50 years." (PMID 24373500, 2013). "Besides, methylations of HMLH1, p16 and CDH1 in gastric-cancer tissue samples at different progress periods do not correlate with the expression of DNMT1 directly." (PMID 21999220, 2011). "First, in the comparison of seven well-know driver genes of gastric cancer, the disproportionate distribution of the CDH1 mutation observed in our GLP cohort and the TCGA non-diffuse GC cohort further supports the previous studies about DGC." (PMID 36450891, 2023). "A retrospective study of CDH1 mutant-negative patients suspected of HDGC found loss of CTNNA1 in diffuse gastric cancer, suggesting that CTNNA1 may be a new susceptibility gene for gastric cancer." (PMID 36741258, 2023). "Additionally, using gastric cancer cell lines and available information concerning CDH1 mutation, DNA methylation, as well as microRNA expression, we observed that the ITGB1/CDH1 inverse relationship is independent of the mechanism leading to E-cadherin inactivation." (PMID 34486077, 2022). "The present study aims to investigate the relationship between CDH1 mRNA expression and HER2-positivity in mGC using a multiplexed gene expression profile in two series of gastric cancer (GC): Series 1 (n = 38): HER2+ and HER2- mGC; Series 2 (n = 36) HER2- GC with and without metastasis." (PMID 35267574, 2022). "However, eradication of the bacteria or creating an EBV vaccine may not fully prevent gastric cancer due to diet, lifestyle and those with a genetic component including the BRCA mutation, CDH1 deletion or Lynch syndrome." (PMID 31569391, 2019).
gastric cancer (continued). "In our study, 50% of the families showed no CDH1 gene alterations, and it is possible that in regions with a high incidence of gastric cancer, such as northern and northeastern Brazil, environmental factors might have induced the different genetic alterations analyzed in this study." (PMID 25180051, 2014). "We then tested DNA from the blood of the 22 patients with familial gastric cancer or early-onset gastric cancer and DNA from non-cancerous gastric tissue of the 18 patients with sporadic gastric cancer to determine the methylation status of the CDH1 promoter region by bisulfite sequencing analysis." (PMID 19671196, 2009). "However, as germline genetic testing becomes more widespread, many CDH1 PV carriers have been identified, including in families with lower penetrance levels or without a history of gastric cancer (GC)." (PMID 39379994, 2024). "CDH1 alterations are believed to be 20% of epigenetic nature and 10% of structural nature, and gastric cancer (GC) patients with CDH1 structural alterations displayed a significantly more dismal prognosis than patients with tumors lacking CDH1 alterations or harboring epigenetic CDH1 aberrations." (PMID 36556227, 2022). "In our cohort, we only identified one CDH1 PGV in a LBC family and there was no history of gastric cancer in this family." (PMID 33763779, 2022). "In order to better identify gastric cancer patients with EMT, EMT and non-EMT patients were distinguished by combining the expression levels of VIM (high expression), CDH1 (low expression), S100A4 (high expression) and EPCAM (low expression)." (PMID 33535187, 2021). "And the recent decline in the non-cardia gastric cancers and increase rate of DGC in the young population < 50 has shifted the focus of researchers to study in detail the link between CDH1 and HDGC." (PMID 33062523, 2020). "Additionally, promoter CpG island (CGI) methylation of tumor suppressor genes such as CDH1 (E-cadherin), CDKN2A (p16), MLH1, and RASSF1A, which is commonly reported in human gastric cancer, has not been observed in MNNG-induced rats." (PMID 41211438, 2025). "Since we did not detect CDH1 expression in MGC803 and BGC823 cells, two gastric cancer cell lines, SGC7901 and MKN45 with active CDH1 expression were used to study the function of Kaiso as a transcription repressor and effects of 14‐3‐3σ expression changes on Kaiso target genes." (PMID 35851744, 2022). "Results showed that expression levels of NKX6.3, CDH1, CDKN1A, and EP300 were decreased while expression levels of NFκB p65, AICDA, CBFβ, APOBEC3A, APOBEC3B, RhoA, ROCK1, ROCK2, PIK3CA, and CCND1 were increased in CagA positive gastric cancers compared to those in CagA negative cases." (PMID 30514953, 2018).
lung carcinoma (550 papers, 1995 to 2026). "We applied functional rescuing experiments in PHF2 knock-out cells and found that CDH1 almost rescued the enhanced lung cancer cell migration and invasion caused by PHF2 deficiency." (PMID 36872368, 2023). "IHC is a widespread method for detecting lymph node micrometastases based on antigen-antibody responders and a low CDH1/CDH2 ratio has recently been shown to be associated with lung cancer micrometastases." (PMID 37509396, 2023). "The same results were observed for lung cancer lines (A549) where treatment with TGF-β1 significantly decreased the gene expression of CDH1 (encoding E-cadherin), increased the gene expression of ACTA2 (encoding α-SMA) and VIM (encoding vimentin)." (PMID 33673178, 2021). "CAFs deliver the transcription factor SNAI1 to lung cancer cells via exosomes, thereby inducing epithelial transformation via CDH1 encoding E-cadherin and VIM encoding Vimentin." (PMID 34193120, 2021). "In the Profile data, of 187 colorectal cancer cases and 246 lung cancer cases evaluated for CDH1 and with confirmed regional or distant disease, only 3 colorectal cancer cases and 9 lung cancer cases had at least one CDH1 mutation." (PMID 29156750, 2017). "Consistent with our results, reduced expression has been reported in lung cancer, and loss of cadherin-1 is a key event leading to loss of adherence, tumorgenicity, and metastasis." (PMID 21170350, 2010). "In depth analysis of lung adenocarcinoma data sets show the diagnostic and prognostic significance of Cdh1 high expression which merits further investigation to establish whether it is a new prognostic marker for lung cancer." (PMID 32015681, 2020). "This suggests that CDH1 mutations could explain detachment of cancer cells from the primary tumor in, at most, roughly 1 in 62 (2%) colorectal cancer cases, and 1 in 27 (4%) lung cancer cases, with observed detachment." (PMID 29156750, 2017). "This notion is also supported by the previous findings that JARID2 promotes the invasion ability of lung cancer cells by recruiting PRC2 to the promoter region of EMT-regulatory genes CDH1 and microRNA-200 family." (PMID 40288646, 2025). "The UBE2C/CDH1/DEPTOR axis forms an oncogene and tumor suppressor cascade regulating autophagy and cell cycle, and UBE2C is a lung cancer target associated with Kras mutations." (PMID 40650277, 2025). "CDH1 (E-cadherin) intron methylation level increased in lung cancer tissues, links to greater invasiveness." (PMID 40725119, 2025). "Consistent observations in human hepatocellular carcinoma cells (Hep G2), lung carcinoma cells (A549), and normal liver cells (L‐02) supported a general correlation between Cdh1 downregulation and CENP‐A upregulation upon administration of MTAs." (PMID 38873820, 2024). "For instance, aberrant CDH1 promoter methylation has been reported in many cancer types in humans, such as gastric, leukemia, breast, and lung cancers." (PMID 37901797, 2023). "Promoter hypermethylation of CDH1 was detected in plasma cell‐free DNA samples of lung cancer patients." (PMID 37901797, 2023). "Hsa_circ_0006692 modulated EMT of lung cancer cells via the stimulation of CDH1, CDH2, VIMENTIN, and MMP7." (PMID 35627232, 2022). "Exosomes containing miRNA-let7e are able to increase CDH1 expression via LSD1 down-regulation to impair lung cancer metastasis." (PMID 35765040, 2022). "It has been reported that CDH1 and ATM germline mutation was associated with colorectal cancer, and MET mutation plays an important role in lung cancer and colorectal cancer development and progression." (PMID 35372080, 2022). "BCRP can also be translocated into the nucleus by interacting with CDH1 promoter to regulate metastasis in lung cancer cells." (PMID 34650973, 2021). "It has been demonstrated that BCRP can be translocated into cell nuclei to regulate the activity of CDH1 promoter in lung cancer." (PMID 34650973, 2021).
lung carcinoma (continued). "In conclusion, to the best of our knowledge, our study is the first to show that Cdh1 functions as an oncogene by inducing self-renewal of lung cancer stem-like cells via the opposing effect of PI3K and MAPK signaling pathways." (PMID 32015681, 2020). "On the other hand, a significantly higher methylation level of CDH1, inducing its inactivation, plays an important role in lung cancer." (PMID 31247897, 2019). "The work presented in this paper focused on the analysis of different expression levels of Dishevelled-1 (DVL1), Dishevelled-3 (DVL3), beta-catenin (CTNNB1) and E-cadherin (CDH1) in brain metastases that originated from primary lung carcinomas." (PMID 24933634, 2014). "The signature was derived from an analysis of 93 lung cancer cell lines that had been previously globally molecularly profiled and sorted by two genes associated with the EMT phenotype, CDH1 and VIM." (PMID 21251323, 2011). "S100P in AD cells and CDH1 in AD and SQ cells were identified as candidate markers of these lung cancer subtypes based on their upregulation and the results of PCA analysis." (PMID 20142997, 2010). "We observed decreased levels of proteins in the serum of lung cancer patients compared to controls, including cadherin-1, LRIG3, sL-selectin, SCRsR, ERBB1 and RGM-C." (PMID 21170350, 2010). "In addition, epigenetic silencing of the CDH1 gene by methylation is of significant importance in lung cancer." (PMID 41394878, 2025). "To examine ERBIN's effect on TGF‐β‐induced EMT, we analyzed breast and lung cancer patient cohorts and found that ERBIN positively correlates with the epithelial marker CDH1 (encoding E‐Cadherin) and negatively correlates with the mesenchymal markers CDH2 (encoding N‐Cadherin) and SNAI1." (PMID 40859866, 2025). "Taken together, our study shows that the UBE2C/CDH1/DEPTOR axis forms an oncogene and tumor suppressor cascade that regulates cell cycle progression and autophagy and validates UBE2C an attractive target for lung cancer associated with Kras mutations." (PMID 36548081, 2023). "Our results showed that, in 34 cases of lung cancer, the CDH1 demonstrated lower expression, while N-cadherin and vimentin had higher levels of expression in tumor tissues, which were significantly different from those in the corresponding noncancerous tissues (n = 34)." (PMID 36711024, 2023). "The experiments indicated that there is a dynamic and inverse correlation between downregulation in the levels of CDH1 (encoding the epithelial cell marker E-cadherin) and the observed increase in the IL2RA (encoding the Treg marker CD25) in stage IV lung cancer patients resistant to chemotherapy." (PMID 36776832, 2023). "CDH1 oncogene, for example, induces self-renewal of lung cancer stem-like cells." (PMID 35784532, 2022). "Thus, high Cdh1 expression is a rather general feature of human cancer and is not limited to lung cancer." (PMID 32015681, 2020). "Indeed, DUOX1 expression status in a panel of lung cancer cell lines strongly correlated with expression of the epithelial marker E-cadherin (CDH1), suggesting that DUOX1 silencing in lung cancer is associated with loss of epithelial characteristics." (PMID 27694834, 2016). "With respect to genes specifying the adhesion complex, mutations in E-cadherin (CDH1) have been found in gastric and colon cancer but have not yet been reported in lung cancer." (PMID 18492263, 2008). "Thus, CDH1 gene expression has a critical role in the progression of lung cancer and can be a valuable independent, favorable prognostic factor, resulting in its expression, which may prove useful for treatment in NSCLC patients." (PMID 37901797, 2023). "Furthermore, CDH1 polymorphisms might also affect the differentiation degree of tumours; preliminary results from our laboratory suggest an overrepresentation of specific CDH1 haplotypes in poorly differentiated lung carcinomas (Emily Wilson, HSc-thesis)." (PMID 18482459, 2008).